EGR1 (early growth response 1)
Diseases named in the same sentence as EGR1 in open-access papers (continued):
Sharing a sentence is not in itself a finding about the gene and the disease.
Insulin resistance (continued). "Mechanistically, increased TSH levels in subclinical hypothyroidism promoted the secretion of cytokines IL-1α, IL-1β and IL-6 by inducing macrophage M1 polarization, which upregulated EGR1 to transcriptionally activate LCN2 and SOCS3 in insulin target cells, thereby exacerbating insulin resistance." (PMID 40523992, 2025). "This study in humans may indicate the importance of the altered exercise response in insulin resistance, and point to MAP kinase and VEGF signaling, possibly through EGR1 and a limited number of transcription factors." (PMID 25984722, 2015). "Furthermore, we verified the expression of Egr-1, which is described as induced by cytokines and hormones through activation of the MAPK pathway and which are related with insulin resistance." (PMID 24453416, 2013).
neuroblastoma (24 papers, 2005 to 2025). Neuroblastoma (NB) is the most common solid, extracranial childhood tumor. "In neuroblastoma cells, Gabra4 expression is controlled by the transcription factor early growth response 1 (EGR-1)." (PMID 40395295, 2023). "Methylated or unmethylated plasmid were then transfected into SHSY-5Y neuroblastoma cells in the presence of an expression vector expressing the EGR1 transcription factor." (PMID 33313982, 2021). "For example, Egr1 is an IEG that induces neuronal differentiation and causes neurite outgrowth in N2 neuroblastoma cells." (PMID 32286359, 2020). "On the other hand neuroblastoma cells which entered the cell death pathway are characterized by activation of EGR1, VEGF, and GDF15." (PMID 29362714, 2017). "Agrin protein expression was compared using M17 human neuroblastoma cells transfected at ~70% confluency with empty vector or a plasmid expressing human Egr-1." (PMID 28824419, 2017). "In this work, it was suggested that nicotine activated EGR-1 expression in the human neuroblastoma SH-SY5Y cell line via the stimulation of the MAPK/ERK signaling pathway and the α7 subtype of nAchR." (PMID 25815723, 2015). "In our previous work we found that the carbachol-mediated induction of EGR-1 in SK-N-SH neuroblastoma cells was transient, tapering off after 1 h, returning to basal levels within 8 h." (PMID 24023725, 2013). "Based on the in-silico results, we tested whether Egr-1 bound directly to the human AGRN gene by performing ChIP using genomic Egr-1: DNA complexes extracted from human M17 neuroblastoma cells." (PMID 28824419, 2017). "Together, these data suggest that agrin protein expression is reduced as a result of increased Egr-1 expression, and that this effect results from regulation at the transcriptional level in human M17 neuroblastoma cells, rat primary neurons and mouse C2C12 myotubes." (PMID 28824419, 2017). "In addition, the expression of several genes associated with growth suppression, including CDKN1A, EGR1, NRG1 and SEL1L, were also enhanced in all S(+)-ibuprofen-treated neuroblastoma cell lines." (PMID 24173829, 2014). "Likewise, an increase of [Ca2+]i is required in carbachol-stimulated neuroblastoma cells and gonadotrophs that express M3 muscarinic acetylcholine receptors to induce the biosynthesis of Egr-1." (PMID 19432968, 2009). "Egr1 is one possible candidate, since in PC12 cells NGF induces Egr1 downstream of ERK and EGR1 is required in the differentiation of neuroblastoma cells." (PMID 21298006, 2011). "In addition, the co-immunoprecipitation of MIDN-Flag with EGR1 was also detected in SH-SY5Y cells, a human neuroblastoma cell line, when treated with insulin (1 μM, 2 h)." (PMID 39264361, 2024). "In our study, we observed downregulation of DBP and upregulation of EGR1 in U2OS cells, which is consistent with previous observations that were carried out using patient-derived lymphoblastoid cells and human neuroblastoma cells." (PMID 34905700, 2021). "Interestingly, PACAP has previously been shown to stimulate EGR1 expression in human neuroblastoma NB1-cells though PAC1 receptor/PKC/MEK1/2 signaling, and PACAP induced neuronal differentiation of PC12 cells requires EGR1 signaling pathways." (PMID 32379800, 2020). "In addition, S(+)-ibuprofen enhanced the expression of some favorable neuroblastoma genes (EPHB6, CD44) and genes involved in growth suppression and differentiation (EGR1, EPHA2, NRG1 and SEL1L)." (PMID 24173829, 2014). "We and others have reported that early growth response-1 (Egr-1), an important transcription factor that regulates p35 expression, is rapidly upregulated after NGF or TNF-α treatment in PC12 cells, and after TGF-β1 treatment in B104 rat neuroblastoma cells." (PMID 23668392, 2013).
neuroblastoma (continued). "Despite this difference in procedure, we see changes in nucleosome positioning in EGR1, LITAF, MLL3 and possibly DHFR, beginning at the 10 minute time point that are consistent with transcriptional changes following one hour nicotine exposure in the SH-SY5Y neuroblastoma cell line." (PMID 26414157, 2015).
leukemia (23 papers, 2006 to 2024). A malignant (clonal) hematologic disorder, involving hematopoietic stem cells and characterized by the presence of primitive or atypical myeloid or lymphoid cells in the bone marrow and the blood. "EGR1 aged-related connected module harbored a gene network known to be implicated in the pathophysiology of leukemia and immune disorders." (PMID 34294125, 2021). "p38 is a regulator of key cell cycle regulators (p21, p16, p19, GADD45), signalling molecules (Chk1, γH2Ax), TFs (Egr1, Fos and Jun) which are inappropriately activated in Trib2 deficient leukaemia cells." (PMID 29670085, 2018). "As reported in this manuscript, total loss of Egr1 allows the leukemia to be initiated and to progress more rapidly." (PMID 29050203, 2017). "In this study we used a mouse model of bone marrow transplantation (BMT) for BCR-ABL driven leukemia and observed that loss of Egr1 in BCR-ABL expressing bone marrow (BM) accelerated the onset of myeloid leukemia." (PMID 29050203, 2017). "We have shown that loss of Egr1 accelerated the development of leukemia in the bone marrow transplantation and transduction model of CML." (PMID 29050203, 2017). "In leukemia, EGR-1 has been implicated in the apoptosis of myeloma cells via interaction with c-JUN while it behaves as a tumor suppressor against the oncogenes E2F-1 and c-MYC." (PMID 22461839, 2012). "Loss of Egr1 was observed to accelerate the development of BCR-ABL driven leukemia in recipient mice, resulting in the development of a more aggressive disease, a significantly shortened median survival time, and increased BCR-ABL expressing leukemic stem/progenitor cells (GFP+Lin-cKit+Sca+)." (PMID 29050203, 2017). "In NPM1-mutated AML, Hox antisense intergenic RNA myeloid 1 (HOTAIRM1) was highly expressed and promoted leukemia cell autophagy by regulating early growth response 1 (EGR1) and unc-51-like autophagy activating kinase 3 (ULK3)." (PMID 39596291, 2024). "EGR1 is able to activate the Wnt/beta-catenin, promotes oncogenesis in tumoral cells but induces apoptosis in leukemia cells." (PMID 37928724, 2023). "The top 15 TFs enriched within the K562 cell associated pattern include TAL1, EGR1, RREB1 and NFE2 which have all been associated with leukemia or, in the case of NFE2, is an erythroid nuclear factor." (PMID 32392348, 2020). "Next, we set out to investigate if there is a difference in leukemia initiating cells by testing the ability of Egr1-/-/BCR-ABL BM to serially transfer leukemia in mice." (PMID 29050203, 2017). "This can be seen in tissue sections from spleens and lungs, where there was more pronounced infiltration of leukemia cells in Egr1-/-/BCR-ABL BM recipients than the WT/BCR-ABL BM recipients." (PMID 29050203, 2017). "This includes reports from this laboratory that constitutive Egr1 overrides leukemia conferred by deregulated c-Myc or E2F-1 in the M1 myeloid leukemic cell line by promoting differentiation." (PMID 29050203, 2017). "Not only did mice display more rapid onset of leukemia, at the time when mice were in a moribund state the disease was more severe in mice transplanted with Egr1-/-/BCR-ABL BM than with WT/BCR-ABL BM." (PMID 29050203, 2017). "There is substantial evidence that early growth response-1 (Egr1) gene, a zinc-finger transcription factor, behaves as a tumor suppressor in leukemia." (PMID 29050203, 2017). "We observed that all the mice transplanted with BCR-ABL-expressing BM null for Egr1 succumbed to leukemia significantly faster than those mice transplanted with BCR-ABL expressing BM WT for Egr1 (P value = 0.0001)." (PMID 29050203, 2017). "This laboratory has demonstrated that constitutive Egr1 can override leukemia conferred by deregulated c-Myc or E2F-1 in the M1 myeloid leukemic cell line by promoting differentiation." (PMID 29050203, 2017).
leukemia (continued). "Dissection of the most influential variables also revealed important differences between models, consistent with the known biological contrasts among these cell types, such as the prominence of EGR1 in ESCs and H3K9me3 in the leukemia cell line." (PMID 26013771, 2015). "Egr1+/−mice develop AML or an MPD-like leukemia with a shorter latency and at a higher overall frequency than WT littermate controls (median survival: Egr1 WT 456 days, Egr1 +/− 397 days, p=0.038)." (PMID 21713073, 2011). "The regulation of TG by EGR-1 has been well documented, although its relevance in leukemia has yet to be determined." (PMID 16670008, 2006). "Amongst those, two genes Egr1 and Trib1 stood out because of their known involvement in leukemia." (PMID 37532789, 2023). "Overall, Egr1 ability to induce terminal differentiation of various mature hematopoietic cells and its tumor-suppressive activity have been explored as potential anti-leukemia therapies." (PMID 35923847, 2022). "This is consistent with its tumor suppressor role; failure to reduce Egr1 may limit or inhibit leukemia initiation and progression." (PMID 29050203, 2017). "There is substantial evidence that Egr1 behaves as a tumor suppressor in leukemia." (PMID 29050203, 2017). "The two diseases observed in our BM transplantation have been reported in other laboratories; the incidence of B-ALL-like leukemia in both WT and Egr1-/-/BCR-ABL induced leukemia may be mouse strain specific." (PMID 29050203, 2017). "Our studies now demonstrate for the first time that Egr1 behaves as a tumor suppressor in a mouse model of BCR-ABL driven leukemia, and provides the impetus to study the effect of altered Egr1 in Acute Myelogenous Leukemia (AML) where the overall five year survival rate remains low." (PMID 29050203, 2017). "Furthermore, we observed increased self-renewal ability of BCR-ABL-expressing Egr1 KO BM, which correlated with increased leukemic potential and higher number of leukemia initiating cells." (PMID 29050203, 2017). "Egr1 can suppress the growth of a number of tumor cells, including leukemia." (PMID 26739353, 2016). "However, the role of EGR1 in leukemia cells is still unclear." (PMID 34615546, 2021). "Later, we identified which ubiquitin ligase might target EGR1 for degradation in leukemia cells." (PMID 34615546, 2021). "Furthermore, to determine whether HOTAIRM1 regulates leukemia cell autophagy and proliferation via EGR1, we performed rescue experiments." (PMID 34615546, 2021). "Here, we summarize the current understanding of the role of EGR1 in the regulation of HSC functionality and the manifestation of leukemia." (PMID 35923847, 2022). "Prompted by these findings, we further investigated the role of the downstream HOTAIRM1 target genes EGR1 and ULK3 in leukemia cells." (PMID 34615546, 2021). "Stable overexpression of miR-146a using a retroviral vector in the murine leukemia cell lines, 70Z/3 and WEHI-231 led to a repression of Egr1 at both the transcript and protein levels." (PMID 25906746, 2015). "Furthermore, nuclear HOTAIRM1 promoted EGR1 ubiquitination by enhancing the MDM2-EGR1 interaction, while cytoplasmic HOTAIRM1 increased ULK3 expression by competitively sponging miR-152-3p, therefore contributing to leukemia cell autophagy and proliferation." (PMID 34615546, 2021). "EGR1 was found to be connected to the aging of human HSC and highlighted a specific cell trajectory contributing to the dysregulation of an inflammatory and leukemia-related transcriptional program in aged human HSCs." (PMID 34294125, 2021).
leukemia (continued). "We found that EGR1 upregulation was connected to the aging of human HSC and highlighted a specific cell trajectory contributing to the dysregulation of an inflammatory and leukemia-related transcriptional program in aged human HSCs." (PMID 34294125, 2021). "Moreover, our results here show that early growth response 1 (EGR1), a transcription factor that controls the early growth response and facilitates tissue healing, is significantly upregulated by ABR in leukemia cells." (PMID 21961024, 2012). "Interestingly, the simulation of Egr1 OA turned out in a complete blockage of B cell development at LMPP stage, indicating that increased expression of Egr1 affects primitive LT-HSC and participate in the development of different types of leukemia." (PMID 33062419, 2020). "The effect of serial passaging of Egr1-/-/BCR-ABL expressing cells, as done in colony assays, on their ability to promote leukemia compared to non-passaged cells would be informative." (PMID 29050203, 2017).
depression (22 papers, 2014 to 2025). "Low levels of Egr1 expression are linked to depression, but they can also serve as a marker for positive pharmacological treatment outcomes when its expression is increased or restored." (PMID 38255760, 2024). "Numerous immediate early genes that are commonly expressed during neuronal activity were down regulated in association with depression, including the top dysregulated gene, EGR1." (PMID 33589676, 2021). "In addition to its association with the development of anxiety- and depression-like states, EGR1 is actively regulated by several classes of antidepressant treatments throughout the brain." (PMID 28321184, 2017). "Here, authors show estrogen-driven Egr1 controls chromatin accessibility sex-dependently, driving gene expression, structural plasticity, and anxiety- & depression-related behaviour." (PMID 41390827, 2025). "In postmortem tissue from patients suffering from major depressive disorder, Egr1 levels in the prefrontal cortex are lower when compared to healthy controls." (PMID 38255760, 2024). "Social defeat stress, a common depression model, reduces Egr1 expression in the prefrontal cortex, confirming Egr1 as biological marker for stress-related depressive disorder." (PMID 35346959, 2022). "Here we perform overexpression and knockdown of Egr1 in vHIP neurons in both sexes and provide functional evidence that Egr1 targets neuronal chromatin sex-dependently, with consequences for gene expression, structural plasticity, and anxiety- and depression-related behaviour." (PMID 41390827, 2025). "Researchers found that its mechanism may be related to the balance of excitement and depression related to plasticity, and Egr-1 and Arc play an important role in learning and memory of humans and animals." (PMID 34781927, 2021). "In addition, using social isolation in rodents, another animal model of depression, it was observed a marked reduction in Egr1 mRNA levels in the hypothalamus, the hippocampus, and the medial prefrontal cortex." (PMID 29755331, 2018). "A recent related study in rats reported that ketamine can promote rapid maturation of hippocampal newborn neurons as defined by the immediate early EGR1 (zif268) gene response, leading to the generation of more neurons within hours in both normal conditions and in a depression model." (PMID 29162814, 2017). "In mice with depression-like behaviors, GAS5 binds specifically to miR26-a to keep EGR1 active, consequently, EGR1 deactivates the PI3K/AKT pathway, subsequently, infectious factors are released and apoptosis of hippocampal cells occurs." (PMID 37620425, 2023). "Notable downregulated genes matching depression were: BDNF, the glucocorticoid receptor, NR3C1, and activity related genes, EGR1, FOS, NR4A1, FOSB, and ARC." (PMID 34997033, 2022). "Some of the common down genes in maternal C57 mice and depression were for the MAP kinase pathway and some of the common down genes included: FOS, EGR1, DUSP1, BDNF, NR4A1, NR3C1, the neuropeptide somatostatin (SST), and one of the its receptors, SSTR2." (PMID 34997033, 2022). "Decreased EGR1 expression was found in post-mortem PFC samples of MDD patients in comparison to healthy individuals and its downregulation was also detected in animal models of depression and anxiety in specific brain areas including the hippocampus." (PMID 36506422, 2022). "In summary, our study reveals that Egr1 is a sex-dependent IEG, capable of initiating and maintaining neuronal chromatin accessibility sex-dependently, with consequences for targeted gene expression changes, structural plasticity, and anxiety- and depression-related behaviour." (PMID 41390827, 2025). "For other IEGs, such as Egr-1, NPAS4, and Arc, their induction by stress makes them molecules of interest in mood disorder research, but causal connections to depression-related behaviors have not yet been uncovered, and continued study of their role in reward circuitry function is needed." (PMID 28503137, 2017).